CAT (catalase)
Diseases named in the same sentence as CAT in open-access papers (continued):
Sharing a sentence is not in itself a finding about the gene and the disease.
neurodegenerative disease (37 papers, 2010 to 2025). A disorder of the central nervous system characterized by gradual and progressive loss of neural tissue and neurologic function. "It is believed that impaired SOD2 is a potential pathogenesis related to oxidative stress in PD and AD, whereas the deficiency or malfunction of CAT is related to the pathogenesis of many age-associated degenerative diseases." (PMID 39273374, 2024). "Deficiency or malfunction of catalase is postulated to be related to the pathogenesis of many degenerative diseases." (PMID 36674472, 2023). "Catalase is one of the most important enzymes involved in ROS detoxification, whose dysregulation leads to many age-associated degenerative diseases." (PMID 33546215, 2021). "The deficiency of catalase is closely related to many degenerative diseases, including PD." (PMID 38672506, 2024). "Earlier reports have also suggested that changes in CAT activity could be related to the pathogenesis of many age-associated degenerative diseases as well with human illnesses associated with oxidative stress including inflammatory diseases." (PMID 37627633, 2023). "Since reactive oxygen species may be implicated in aging process and in degenerative diseases, we used antioxidant compounds as catalase, thiourea and dipyridyl in the lysogenic induction test." (PMID 21637431, 2010). "Glyphosate’s effect on reducing catalase enzyme activity and promoting amyloid-beta (Aβ) accumulation in this model reinforces its potential role as an environmental factor contributing to neurodegenerative diseases, particularly Alzheimer’s." (PMID 40667448, 2025). "Nanozymes are mainly used in neurodegenerative diseases to decrease inflammation, scavenge ROS, and mitigate it through CAT, POD, and SOD-like antioxidant activities." (PMID 40332015, 2025). "It has been established that there is a direct relationship between neurodegenerative diseases and oxidative stress which is considered by the reduced activity of antioxidant enzymes such as CAT, GPx, and SOD." (PMID 40236290, 2025). "Several antioxidants including superoxide dismutase, catalase, vitamin E and ascorbic acid have been investigated for their effects in attenuating neurotoxicity and promoting neuroprotection in neurodegenerative diseases." (PMID 37108458, 2023). "Catalase constitutes the main peroxisomal antioxidant H2O2-degrading enzyme, and the perturbation of catalase activity is related to many neurodegenerative diseases." (PMID 36671029, 2023). "The subacute IMI exposure can cause toxic effects, which can lead to a variety of neurodegenerative diseases, depending on the dose which its outcomes AChE inhibition; changes in antioxidant status caused by increased lipid peroxidation and a decrease in GSH, CAT, and SOD." (PMID 37727350, 2023). "Previous studies pointed out that antioxidant enzymes such as SOD, CAT, and GPx are crucial for protecting mitochondria from oxidative stress since the production of reactive species leads to mitochondrial damage, which is a key factor in the occurrence of neurodegenerative diseases." (PMID 35449538, 2022). "NMN has been shown to mitigate these effects by modulating oxidative stress markers (e.g., SOD, CAT) and inflammatory cytokines (e.g., TNF-α, IL-1β, IL-6), thus underscoring its potential in protecting against neurodegenerative diseases." (PMID 40276601, 2025). "Manganese-based nanozymes with catalase (CAT) and SOD-mimicking activities serve as free radical scavengers in neurodegenerative diseases, reducing oxidative damage and neuroinflammation by converting •OH, O2•− and H2O2 into non-toxic H2O and O2." (PMID 40619552, 2025). "Catalase (CAT), a potent antioxidant used to treat neurodegenerative diseases by inhibiting inflammation and protecting dopaminergic neurons, is limited by the impermeability of the blood–brain barrier to most therapeutic agents." (PMID 39660145, 2024).
neurodegenerative disease (continued). "In several well-designed chronic and degenerative disease models, EA displays the capability to lower the oxidative stress markers, such as malondialdehyde (MDA) and nitric oxide, and to increase the antioxidant enzyme (e.g., catalase (CAT), superoxide dismutase (SOD)) activities." (PMID 35204135, 2022).
bacterial infection (30 papers, 2015 to 2025). "Over-representation of certain bacterial infections caused by catalase positive microorganisms, such as Staphylococcus aureus, Pseudomonas, and Burkholderia cepacia, as well as fungal species, such as Aspergillus, are common." (PMID 33114493, 2020). "This exceptional photodynamic antimicrobial capability of CAT–Ce6 NCs in hypoxic condition lays a solid foundation for subcutaneous bacterial infection treatment." (PMID 40463499, 2025). "CAT activity in transgenic tobacco can result in serious HR and effectively control bacterial infection." (PMID 36694139, 2023). "POD, SOD, and APX activities were similar to those during bacterial infection, whereas CAT activity increased." (PMID 37628673, 2023). "According to our findings, R. solanacearum attack on eggplants in the biochar-based soil amendment considerably influenced the levels of catalase and peroxidase synthesis, which in turn helped to mitigate the stress by bacterial infection." (PMID 37564063, 2023). "Collectively, our findings reveal a mechanism of antimicrobial blue light and fuel a catalase-targeted strategy to combat clinical multidrug-resistant bacterial infections." (PMID 35446788, 2022). "Collectively, these in vivo data provide the foundation for exploring the clinical utility of our catalase-targeted therapy against multidrug-resistant bacterial infections." (PMID 35446788, 2022). "Taken together, our findings offer a catalase-targeting phototherapy approach against multidrug-resistant bacterial infections." (PMID 35446788, 2022). "Overall, the data suggest that P. aeruginosa ttcA plays a critical role in protecting against oxidative stress via catalase activity and is required for successful bacterial infection of the host." (PMID 30089777, 2018). "During bacterial infection, P. aeruginosa OxyR upregulates katA39 and derepresses ttcA expression to increase catalase activity in response to H2O2 generated via host defence mechanisms." (PMID 30089777, 2018). "Additionally, nanoenzymes with superoxide dismutase (SOD), catalase (CAT), and other antioxidant enzymes can remove excessive ROS to promote wound healing or reduce inflammatory responses caused by bacterial infection." (PMID 39339224, 2024). "Furthermore, CAT activity was more notably induced post-bacterial infection in the MOS supplemental groups, thereby protecting cells from oxidative damage." (PMID 35784342, 2022). "This demonstrated the crucial role of CAT and SOD genes in immune responses to eliminate ROS during bacterial infection." (PMID 40276584, 2025). "It has been shown that ABPs improved the intestinal flora and showed resistance to bacterial infections, and also significantly increased the expression of intestinal antioxidant genes SOD1 and CAT to enhance the antioxidant capacity of broiler chickens." (PMID 40351762, 2025). "One of the functions of catalase (CAT), as an endogenous antioxidant enzyme, is to remove excessive reactive oxygen species (ROS) generated by bacterial infection." (PMID 38799475, 2024). "From four antioxidants, three recombinant proteins, i.e., CAT, GPX-1, GST-mu, were studied for the relative percentage survival of L. rohita against bacterial infection; however, rLrCuZnSOD was found toxic to fish that needs further investigation." (PMID 38275638, 2023). "Toward clinical translation, the synergy between photoinactivation of catalase and H2O2/antibiotics is most suitable for superficial bacterial infections due to limited penetration depth of 410 nm light." (PMID 35446788, 2022). "We further evaluated the synergy between photoinactivation of catalase and H2O2 using a bacterial infection murine model." (PMID 35446788, 2022). "Again, we did not observe a significant change in catalase production between the established fungal and immediate bacterial infections." (PMID 35862772, 2022).
bacterial infection (continued). "Similarly, as major defensive enzymes, SOD, CAT, and GPX showed significantly increased activity after bacterial infection, suggesting intensive use of overgenerated H2O2 in the oxidation of phenolics, which can be inhibitors of bacterial and fungal growth." (PMID 30999692, 2019). "According to the present findings, R. solanacearum infection on eggplants in the biochar soil amendment (with and without BCA) also considerably influenced the levels of catalase and peroxidase synthesis, which in turn helped to mitigate the stress by bacterial infection." (PMID 38725679, 2024).
nephropathy (28 papers, 2011 to 2025). A nonspecific term referring to disease or damage of the kidneys. "Notably, impaired FA oxidation has been associated with CKD supporting a role for catalase in renal disease." (PMID 32481548, 2020). "Decline in the activity of catalase is expected to result in the accumulation of harmful H2O2, which can cause DNA damage and initiate renal disease." (PMID 40271532, 2025). "Curcumin can also upregulate the expression of SOD, GPX and catalase via Nrf2 to ameliorate mitochondrial oxidative stress, and further restore the activities of renal mitochondrial respiratory enzyme in various kidney diseases." (PMID 37007023, 2023). "Catalytic antioxidants, especially mimics of specific redox enzymes such as SOD, CAT, and GPx, have been demonstrated to have therapeutic advantages in various experimental models of kidney disease." (PMID 33477607, 2021). "It is also not surprising that enhancement of antioxidants such as NQO1, catalase, and the SODs are protective in renal disease." (PMID 27804998, 2016). "In addition to reduced SOD and catalase levels, several rodent models of kidney disease and patients with CKD have been shown to present decreased levels of GSH early on contributing to disease progression." (PMID 32481548, 2020). "In the process of kidney diseases such as DKD, excessive ROS causes renal function damage, Keap1 increases, and Nrf2 activation decreases, reduce the production of antioxidant related proteins, such as superoxide dismutase(SOD)-1, heme oxygenase (HO)-1, and catalase (CAT)." (PMID 36234757, 2022). "Thymoquinone can increase the expression of mitochondrial ROS scavenging enzymes and antioxidant molecules, such as GPX, catalase, SOD and GSH, and restore renal mitochondrial viability via Nrf2 in various kidney diseases models." (PMID 37007023, 2023). "The prototype salen Mn complex (EUK-8) and the improved CAT mimetics (EUK-134 and EUK-189) are effective in a wide range of disease models, including kidney disease." (PMID 33477607, 2021). "Myrcene treatment resulted in significant upregulation of antioxidant enzymes GSH and CAT and downregulated MDA level, suggesting an antioxidant role for myrcene in renal diseases." (PMID 33007969, 2020). "Furthermore, L-carnitine can also restore anti-oxidative molecules and enzymes, such as GSH, SOD, catalase and GPX, in kidney diseases." (PMID 37007023, 2023). "In addition, the CAT protein that was found downregulated in the cortex of the late DKD animal models (db/db mice) was investigated as a control since it is the most studied and best-characterized peroxisomal antioxidant enzyme in kidney disease." (PMID 35203426, 2022).
cardiovascular disease (26 papers, 2012 to 2025). "Catalase deficiency or dysfunction is related to the pathogenesis of some disease conditions such as cardiovascular diseases and neurological disorders." (PMID 37111107, 2023). "Several studies have reported the remarkable increase in MDA but decrease in TAC and catalase activity in aging, relating to risks of cardiovascular diseases and all-cause mortality." (PMID 34203897, 2021). "In humans, mutations of mitochondrial antioxidants (e.g., SOD2, catalase, GPx, and TrxR) increase the risk for cardiovascular diseases." (PMID 32424140, 2020). "Although emerging evidence indicates that catalase is cardiovascular-protective, particularly against oxidative stress-associated cardiovascular disorders and Ang II-induced hypertrophy, molecular switches that modulate its expression or activity in cardiovascular cells are rarely reported." (PMID 34439471, 2021). "Interestingly, low plasma catalase is associated with a high risk for one form of cardiovascular disease." (PMID 23013352, 2012). "The reduction in SOD and CAT activity is indicative of a state of exacerbated oxidative stress, common in cardiovascular diseases that may contribute to progressive tissue damage." (PMID 41117296, 2025). "The effect of PPARδ ligands on catalase expression may mediate many of the functions of PPARδ, implicating it as a key target for therapeutic intervention in ROS-related cardiovascular disorders such as hypertrophy." (PMID 34439471, 2021). "Increase in miRNA-208 expression and decrease in miR-1 expression along with significant decreases in the activity of antioxidant enzymes (CAT, SOD, and Gpx) have also been observed in heterogenic group of cardiovascular disease (CVD) patients." (PMID 36499336, 2022). "Their potential prognostic value in the clinical outcome of cardiovascular diseases (CVD) has also been highlighted with MDA, SOD, and CAT being one of the most promising biomarkers in this regard." (PMID 31929853, 2019). "Numerous studies have shown that Nrf2 downstream targets, such as NQO-1, CAT, and SOD, have significant antioxidant effects on various cardiovascular diseases." (PMID 31934264, 2019). "Inductions of the Nrf2-regulated enzymes [e.g., superoxide dismutase (SOD), HO-1, catalase (CAT), and glutathione peroxidase (GPx)] are beneficial for the therapy of these cardiovascular diseases." (PMID 30050659, 2018). "Therefore, the enhancement of CAT activity by the HMH peptides, especially in the adult rats, could also have contributed to the observed decrease in plasma TPx levels, which can decrease the risk or pathological intensity of cardiovascular disease." (PMID 25493943, 2014). "The analysis of SOD activity provided further confirmation of the role of impaired anti-oxidant status in facilitating cardiovascular disease, although catalase showed no predictive value of cardiovascular events." (PMID 36246071, 2022).
metabolic disorders (26 papers, 2016 to 2025). "There is a lot of evidence that genetic alterations of CAT and its promoter represent a risk factor for metabolic diseases." (PMID 33138337, 2020). "The decreases in SOD and CAT activities could be related to the metabolic disorder due to B deficiency or other unknown reasons." (PMID 39030471, 2024). "This may be because the level of CAT inhibition caused by 13-HODE only resulted in metabolic disorder, which is insufficient to induce cellular senescence." (PMID 38071367, 2023). "Interestingly, the SOD, POD, and CAT activity of K. obovata sharply dropped when initially subjected to the freezing tress, which partly attributed to the extreme low temperature (-4.1 °C) causing serious metabolic disorders." (PMID 36529723, 2022). "Several studies support our findings, showing elevated levels of oxidative stress markers along with downregulated SOD, catalase, and GPx in the placentas of mothers with metabolic disorders." (PMID 39409195, 2024). "The metabolic and regulatory activities, including catalase stimulation, calcium regulation, and antianginal effects, indicated prodigiosin’s potential for managing metabolic disorders and cardiovascular conditions." (PMID 39587466, 2024). "CAT seemed to be impacted by both metabolic diseases even more, since a significantly lower activity of this antioxidant enzyme was recorded in both experimental groups as opposed to the control (P < 0.05)." (PMID 36405233, 2022). "Metabolic diseases cause the depletion of superoxide dismutase (SOD), catalase (CAT), glutathione reductase, and glutathione peroxidase (GPx) activities, and also impair the non-enzymatic oxidative system, causing reduced thiol, vitamins, and minerals." (PMID 36230142, 2022). "These hydrolysates exhibited dual functionality: direct ROS scavenging and activation of antioxidant enzymes (SOD, CAT, GSH-Px) in oxidative-stressed HUVECs at 200 μg/mL, demonstrated therapeutic potential for metabolic disorders." (PMID 40458704, 2025). "Upregulation of key antioxidant enzymes such as superoxide dismutase (SOD), catalase, and glutathione (GSH) plays a critical role in protecting against oxidative damage and mitigating the progression of metabolic disorders." (PMID 41516183, 2025). "Presenilin 1 (PSEN1), catalase (CAT), glutathione-S-transferase (GST) andparaoxonase 1 (PON1) play a vital role in prediction, diagnosis and therapyof metabolic disorders." (PMID 35976206, 2022). "Some reports also confirmed that a compensatory mechanism of metabolic disorders occurs in PCOS patients, as oxidative stress markers, such as superoxide dismutase and catalase, were detected in the normal range in women with PCOS." (PMID 33455575, 2021). "Thus, strategies based on catalase may be therapeutic against metabolic diseases." (PMID 27597806, 2016). "In addition, metabolic disorders deplete antioxidants such as glutathione (GSH), reducing the body’s antioxidant capacity and leading to a decrease in the activity of antioxidant enzymes such as SOD and catalase (CAT)." (PMID 40969373, 2025).
liver (15 papers, 2005 to 2025). "The enhanced metabolic capacity of ethanol through the catalase pathway will accelerate the generation of the toxic molecule acetaldehyde and the development of alcohol fatty liver and related liver injury in diabetic and obese individuals." (PMID 40496347, 2025). "Our native PAGE data show that the alcohol control and liver cirrhotic groups had lower catalase (CAT) activity than control groups." (PMID 40271532, 2025). "These antioxidant enzymes—SOD, GPx, CAT—hold pivotal roles in countering alcoholic liver injury, aiding cells in converting detrimental free radicals into innocuous water and oxygen through hydrogen peroxide mediation." (PMID 37891875, 2023). "When compared to the effects of taVNS and standard chemotherapy against DMH induced colon carcinogenesis, taVNS was more effective in regulating the TBARs (all taVNS treatments), catalase (all taVNS treatments), and GSH (taVNS 4)." (PMID 31164817, 2019). "DEX can cut down on oxidative stress responses and lessen liver damage in the rat liver IR model by boosting the activity of SOD, CAT, and GSH-PX41." (PMID 39955447, 2025).
neurological diseases (12 papers, 2014 to 2025). "Defects in catalase have been implicated in a number of neurological disorders, including AD." (PMID 37038196, 2023). "Based on the anti-oxidative properties of Pur in nervous system diseases, we evaluated CAT activity, as well as the levels of GSH and MDA in the rat serum and cortical neurons." (PMID 34356602, 2021). "It has been reported that other antioxidant enzymes, such as superoxide dismutase (SOD), catalase and glutathione peroxidase (GPx), are compromised in people with neurological diseases, including MS, suggesting their importance in protection against ROS within the brain." (PMID 37239272, 2023). "Thus, the study suggests that nanoparticle-loaded catalase may be used as a therapeutic agent in oxidative stress-related neurological diseases." (PMID 31827713, 2019). "Additionally, targeting oxidative stress pathways such as glutathione, and catalase may help mitigate the effects of MMP activity and reduce neurological disorders." (PMID 40356950, 2025).